EGFR (epidermal growth factor receptor)
Diseases named in the same sentence as EGFR in open-access papers (continued):
Sharing a sentence is not in itself a finding about the gene and the disease.
tumor (continued). "In both human and mouse tumors (hepatocellular carcinoma and colorectal carcinoma), EGFR expression in macrophages promotes tumor development." (PMID 37601668, 2023). "A study reported that gambogic acid in combination with EGFR-TKI effectively inhibited EGRF-T790M mutated lung adenocarcinoma cell lines and suppressed tumor volume growth in vivo." (PMID 36770689, 2023). "Both exogenous PGE2 (produced by the tumor microenvironment) and endogenous PGE2 (produced by the tumor cell itself) promote EGFR phosphorylation through direct or indirect mechanisms." (PMID 37190301, 2023). "By testing serial dilutions of tumor DNA samples with Tier I/II variants (BRAF V600E, KRAS G12C, and EGFR exon 19 deletion p.L747_E749del), the LOD for accurate and reproducible variant calling was determined to be 5% of variant allele frequency." (PMID 37483495, 2023). "Previously, we found that the combination of EGFR antibody and kinase inhibitor led to sustained tumor control in patients with EGFR 20ins-postive NSCLC9,10." (PMID 37308490, 2023). "The binding specificity of cetuximab-IR700 dye conjugate (anti-EGFR-IR700 antibody conjugate; CTX-IR700) to epidermal growth factor receptor (EGFR) was evaluated in vitro on BxPC-3 pancreatic adenocarcinoma tumor cells by flow cytometry." (PMID 35776159, 2023). "After analysis, we found that samples with different MMP11 expression profiles in EGFR-mutant LUAD had different infiltration of immune cells in the tumor parenchyma." (PMID 36756152, 2023). "Our results revealed that IgA anti-EGFR therapy led to a 50% reduction in tumor cells recovered from the peritoneum." (PMID 37444515, 2023). "After combining with its receptor, EGFR can phosphorylate and activate downstream signaling pathways to regulate the invasion and migration of tumor cells." (PMID 36814816, 2023). "Cetuximab-IONP bound/internalised GBM cells more efficiently than other EGFR-targeted drugs, resulting in increased longevity and the capacity to halt tumour recurrence or metastasis." (PMID 37375846, 2023). "Immunohistochemistry data demonstrated that p-EGFR levels were significantly elevated in treated tumor xenografts." (PMID 37020035, 2023). "In HCC cells such as HEP3B and SMMC7721, the overexpression of YTHDF2 suppressed cell proliferation via destabilizing EGFR mRNA and, thus, acting as a tumor suppressor." (PMID 37631344, 2023). "CRISPR/Cas9-mediated elimination of EGFR significantly inhibits tumor cell growth and activates the mitogen-activated protein kinase (MAPK) (p-ERK1/2) pathway." (PMID 37601068, 2023). "Mutations in the MET gene lead to abnormal expression of the MET axis, promoting the migration and invasion of tumor cells, as well as resistance to inhibitors targeting EGFR and VEGFR." (PMID 37444584, 2023). "Simultaneously, stimulating microglia to express EGFR also facilitates tumor cell invasion and growth." (PMID 37700840, 2023). "SC4MOL knockdown sensitizes tumor cells to epidermal growth factor receptor-inhibiting chemotherapeutics." (PMID 36958722, 2023). "Ablation of each ERBB family member, especially the loss of EGFR or ERBB2/HER2, altered signaling downstream of the other three ERBB receptors and decreased cell proliferation, migration, and tumor growth." (PMID 37341059, 2023). "When compared to current mouse models, our humanized mouse model replicates human EGFR mutant tumor growth physiology, pathology, immunology, and response to osimertinib treatment." (PMID 37169941, 2023). "From an updated multicenter study, including patients with EGFR mutated (EGFR+), Kirsten rat sarcoma (KRAS+) and EGFR/KRAS wildtype metastatic NSCLC, all patients with available formalin-fixed paraffin-embedded (FFPE) tumor samples were selected." (PMID 37213294, 2023). "64Cu-GE11 PMNPs displayed enhanced tumor accumulation due to EGFR targeting effects, which was confirmed by both PET imaging and biodistribution studies in vivo EGFR-positive colorectal HCT116 tumor model." (PMID 37298101, 2023).
tumor (continued). "The results of the SAKK phase III trial, in which the anti-EGFR agent cetuximab was added to preoperative chemoradiotherapy, showed improved local tumor control with reduced local tumor recurrence." (PMID 37046849, 2023). "Tumor-associated macrophages (TAMs), one of the central immune cells in the TME of NSCLC, play an essential role in mediating EGFR-TKIs resistance." (PMID 37649478, 2023). "Vaccination with the DC, pulsed with recombinant glutathione-S-transferase (GST)-EGFR fusion protein, has been shown to induce a significant anti-tumor immune response against HNSCC, both in vitro and in vivo, in a mice model." (PMID 36992219, 2023). "EGFR plays a vital role in numerous processes that affect tumor growth and progression, including proliferation, differentiation, angiogenesis, inhibition of apoptosis, and invasiveness." (PMID 37501139, 2023). "Overexpression of EGFR has been reported in a variety of cancers, where it is involved in tumor progression and metastasis." (PMID 37081888, 2023). "We report here thedevelopment of two different sensing strategiesbased on the use of antigen-conjugated nucleic acid strands for thedetection of a bispecific antibody against the tumor-related proteinsMucin1 and epidermal growth factor receptor." (PMID 37856082, 2023). "Fc IgG1 induces Fc receptor-mediated NK cytotoxicity and macrophage phagocytosis and anti-EGFR tethers CCL5-Fc to tumor cells." (PMID 37325516, 2023). "These glycosylation changes reduce galectin-3-mediated tumour cell-cell interaction, cell adhesion and EGFR activation and decrease galectin-3-mediated tumour growth in a chick embryo model." (PMID 37612278, 2023). "On the other hand, EGFR activation alone promotes the upregulation of both COX2 and mPGES1 enzymes associated with increased PGE2 production and enhanced tumor aggressiveness." (PMID 37190301, 2023). "In Drosophila tumor models, the overexpression of EGFR alone leads to hyperplasia of the affected tissue, but without progressing to a malignant tumor." (PMID 37190033, 2023). "The inhibition of JorA on EGFR and Ki67 was also verified in the xenografted tumor section of the mouse model." (PMID 37587470, 2023). "Numerous studies have shown that ER stress suppresses tumor growth and overcomes EGFR-mediated resistance by inhibiting the phosphorylation of EGFR." (PMID 36768961, 2023). "Note that EGFR functions were studied for a long time on immortalized cells, obtained mostly from tissues of tumor origin." (PMID 37686213, 2023). "Next, we used the mouse subcutaneous xenograft model to evaluate the effect of combination of PELI1 knockdown and EGFR inhibition on tumor growth." (PMID 36841821, 2023). "It is known that the EGFR signaling pathway is a significant element in the onset and progression of many neoplastic diseases." (PMID 36766810, 2023). "Studies have shown that the tumor microenvironment (TME) also mediates EGFR-TKIs resistance in NSCLC." (PMID 37649478, 2023). "When loaded with siRNA against HPV16-E6/E7, the superior tumor suppression effect of anti-EGFR-LNPs was also observed, with a 50% greater reduction of tumor volume that was achieved compared to isotype control LNPs in a xenograft HPV-positive tumor model." (PMID 38516300, 2023). "The development of novel anti-tumor drugs targeting wild-type EGFR with improved pharmaceutical profiles and reduced toxicity thus remains an unmet medical need." (PMID 37762316, 2023). "There is mounting evidence that EGFR/Ras/Raf/Erk1/2 cascade activation facilitates key tumor progressions, including proliferation, migration, metastasis, and angiogenesis, by regulating downstream pathways." (PMID 36765716, 2023). "Glutamine deprivation in tumor cells activates EGFR/ERK/C‐JUN signaling and then upregulates the expression of PD‐L1 in tumor cells, which weakens the antitumor immune response." (PMID 37860928, 2023).
tumor (continued). "Contrary to normal cells with tightly controlled EGFR pathways, tumour cells exhibit dysregulated EGFR signalling due to receptor overexpression and/or mutation." (PMID 37548154, 2023). "It has been suggested that EGFR overexpression confers enhanced radioresistance and lower sensitivity to Cisplatin therapy in tumour cells." (PMID 38414930, 2023). "The development of molecular agents targeting the EGFR pathway offers attractive avenues for anti-tumor effects, and the presently available EGFR tyrosine kinase inhibitors in widespread clinical use are gefitinib and erlotinib." (PMID 37063281, 2023). "Oncogenic transformation of EGFR in tumor cells can lead to angiogenesis, accelerated cell proliferation, inhibition of apoptosis, cell motility, and metastasis." (PMID 37111291, 2023). "Nimotuzumab (NTZ) is a humanized anti-EGFR monoclonal antibody that can block the EGFR on cells and enhance the radiation sensitivity of tumor cells, thus improving the radiotherapy effect on tumors." (PMID 36814816, 2023). "In mice bearing DFCI081 xenografts (harboring EGFR Del19 and METamp), tepotinib, alone or combined with EGFR-TKIs (rociletinib, erlotinib, or afatinib), induced complete tumor regression." (PMID 36999986, 2023). "Yet it will be interesting to examine if EGFR inhibition can induce tumor-lineage plasticity in HCC." (PMID 38030644, 2023). "One study examined co-transfection of IL-12 and (salmosin) Sal genes via anti-EGFR immunolipoplexes inhibited tumor growth and pulmonary metastasis (p < 0.001)." (PMID 37612696, 2023). "In vivo a short-term xenograft mouse model confirmed the improved therapeutic efficacy of EGFR antibodies against sialic acid depleted, by a sialyltransferase inhibitor, tumor cells compared to untreated cells." (PMID 37346044, 2023). "VEGF and EGFR can exaggerate tumors through the exertion of both indirect and direct effects on tumor cells." (PMID 37834474, 2023). "Based on the tumor RAS/BRAF mutational status, therapies involving anti-EGFR monoclonal antibodies (cetuximab, panitumumab) can be used." (PMID 38008721, 2023). "Indeed, we show that patients with EGFR mutated and miR-200 sign-down tumors are at higher risk of relapse independently of tumor stage, and, at the opposite, that patients with EGFR mutated and miR-200 sign-up tumors do not relapse and might not need adjuvant treatment." (PMID 37189151, 2023). "EGFR is overexpressed in a variety of highly aggressive tumors and is a promising target for tumor therapy." (PMID 37919282, 2023). "Another study confirmed that anti-EGFR VHHs are more homogeneously distributed throughout the tumor, whereas the anti-EGFR mAbs Cetuximab are confined to the core of the tumor." (PMID 37746282, 2023). "Codons 12/13 in exon 2 of the KRAS gene lead to continuous activation of the EGFR signaling pathway that accelerates tumor cell proliferation." (PMID 37924117, 2023). "Both wild-type and mutant EGFR were detected in EVs isolated in the plasma of patients affected by GBM and in GBM xenograft mice, reflecting the mutations found in the tumour." (PMID 37296932, 2023). "ATO diminished the number of tumor cells from patients with WT and mutant EGFR, down-regulated the expression or phosphorylation of EGFR, pmTOR, PI3K, PTEN, and p4E-BP1, and up-regulated the expression of LC3." (PMID 37371816, 2023). "Conversely, whereas the 60% of GBM samples with 2 copies of CBX3 are also normoploid for EGFR gene, all tumor samples with multiple copies of CBX3 gene display low or high gain increase of EGFR gene CN." (PMID 37633946, 2023). "The rapid shrinkage of EGFR-TKI itself can lead to the reduction of the overall tumor blood vessels, masking the benefits of anti-angiogenesis." (PMID 37316870, 2023). "In in vitro studies, lapatinib has been shown to be an effective growth inhibitor of tumor cells overexpressing EGFR or HER2 receptors in a cell-based proliferation assay using protein staining." (PMID 38201251, 2023).
tumor (continued). "In the meantime, intense decreases in epidermal growth factor receptor activity as well as hexokinase-2 expression were detected in kaempferol-treated tumor tissue." (PMID 37239974, 2023). "This bsAb was designed to be minimally active ‘en route’, while providing multivalent and tumor-localized crosslinking of CD27 when bound to EGFR+ cancer cells." (PMID 37545491, 2023). "Tepotinib in combination with afatinib or erlotinib also moderately inhibited tumor growth but tepotinib combined with the third-generation EGFR-TKI rociletinib induced complete regression." (PMID 36999986, 2023). "Our preclinical studies in NSCLC models demonstrate the potential for improved tumor targeting with EGFR-targeted SAR-MSCs." (PMID 37376189, 2023). "Untreated tumors showed EGFR expression in tumor cells within the “ecological transition zone,” where tumor and host cells interact." (PMID 37501404, 2023). "Activation analysis of typical tumor pathways showed that pathways related to cancer progression, such as Androgen, EGFR, Estrogen, Hypoxia, JAK-STAT, and MARK were significantly activated in the high-risk group." (PMID 38097948, 2023). "The EGFR is, however, also closely related to several cancer-promoting processes, namely tumor cell proliferation, angiogenesis, increased cell motility, metastatic growth and apoptosis-suppression." (PMID 37259420, 2023). "EGFR immunoreactivity was also observed in 20.6% (7/34) of IDH1mt tumours, although weak and limited, and unrelated to tumour grade." (PMID 37568909, 2023). "In preclinical models, the combination of savolitinib and erlotinib (a first-generation EGFR-TKI) demonstrated significant tumor suppressive effects in NSCLC cell line models with MET amplification." (PMID 37835402, 2023). "In fact, EGFR/ Akt signaling pathway plays an irreplaceable role in the tumorigenesis and progression, and is involved in tumor cell proliferation and invasion." (PMID 37808589, 2023). "Taken together, these data proved that acacetin suppressed GC xenograft tumor growth by decreasing EGFR phosphorylation in vivo." (PMID 37266143, 2023). "Using targeted sequencing, EGFR‐LFD was identified in tumor tissue of 13 patients and plasma of 4 patients." (PMID 36622089, 2023). "EGFR-amplified tumours tended to retain their EGFR-amplified status in recurrence, even despite targeted treatment in three cases." (PMID 36765632, 2023). "Together, these data provide evidence that the compoundcan both engage EGFR and release 5FU in tumor cells." (PMID 37647129, 2023). "Activation of EGFR can promote proliferation, invasion, and metastasis of tumor cells, as well as inhibit apoptosis of tumor cells, thus inducing tolerance to radiotherapy and chemotherapy." (PMID 37996813, 2023). "The favorable penetration ability of anti-EGFR-iRGD VHHs was reflected by the change of tumor volume in a mice model." (PMID 37746282, 2023). "In conclusion, CD27xEGFR is a novel DVD-Ig bsAb targeting CD27 and EGFR, that has the potential to re-activate T cell immunity in EGFR+ carcinomas through its interaction with tumor-reactive and exhausted CD27+CD8+ TILs." (PMID 37545491, 2023). "Knockdown of GSDMD has been demonstrated to suppress tumor progression by promoting the mitochondrial apoptotic pathway and inhibiting the epidermal growth factor receptor (EGFR)/Akt pathway." (PMID 38066523, 2023). "The best samples for EGFR testing are fresh tumor tissues and paraffin-embedded specimens, but it is difficult to obtain tumor tissues from some patients with advanced NSCLC." (PMID 36835972, 2023). "On the contrary, the high expression of IFIT1 and IFIT3 in OSCC contributes to gefitinib's anti-tumor effect by enhancing p-EGFR recycling." (PMID 37980495, 2023).
tumor (continued). "Clustering the most co-cited references reveals the main research directions in this field, with tumor microenvironment and EGFR as the largest clusters, indicating their importance as core research foci." (PMID 38259287, 2023). "Compared to patients without primary resistance, more females (p = 0.018), patients treated at later lines (p = 0.034) and patients with EGFR+ tumours (p = 0.018) encountered primary resistance." (PMID 37345072, 2023). "Overexpression and mutation of EGFR leads to constitutive activation of the EGF/EGFR pathway, which is associated with increased tumor proliferation and chemotherapy resistance and remains a major clinical challenge for cancer therapy." (PMID 37762316, 2023). "Off-target resistance is mediated by the shift of oncogenic dependence that allow tumor to bypass EGFR blockade." (PMID 37308490, 2023). "On the other hand, lapatinib, an anti-HER2 TKI with a weaker inhibitory effect on EGFR than afatinib, was less effective in inhibiting tumor growth (IC50: 1.8 μM)." (PMID 36690964, 2023). "EGFR overexpression or aberrant activation has been found in several tumors and drives tumor progression, inducing cancer cell growth, migration, invasion, and metastasis." (PMID 37190301, 2023). "In tumor cells, the EGFR hyperactivation increases drug efflux, DNA damage repair, anti-apoptosis, and stem-like properties." (PMID 37165076, 2023). "The inhibitory effect of sub-signals and EP-stimulating factors to be stimulated by EGFR and Src was observed in tumor tissues." (PMID 37686097, 2023). "Specifically, consistent with their opposing effects on tumor initiation and progression, TGFβ and EGFR signaling were significantly elevated in primary tumors but diminished in metastases." (PMID 37463901, 2023). "NR1H3 is also able to suppress the activity of the epidermal growth factor receptor (EGFR) promoter, reducing tumor cell growth and proliferation." (PMID 38023258, 2023). "All ALK inhibitors were solely been indicated for patients with ALK-positive tumours (defined by a validated method), whereas EGFR inhibitors (specifically erlotinib) were also used to some extent outside of EGFR-positive patients." (PMID 36900294, 2023). "Increasing evidence suggests that miRNAs are key regulatory molecules that modulate the sensitivity of tumor cells to EGFR-TKIs." (PMID 38169723, 2023). "EGFR was overexpressed in the present study, with the observation of immunoreactivity in 56.6% of the tumor cells analyzed." (PMID 37194849, 2023). "Niraparib activated anti-tumor CD8+T cells in the tumor microenvironment through the STING/TBK1/IRF3 pathway in EGFR-mutant NSCLC." (PMID 36865554, 2023). "Tumor antigens such as epidermal growth factor receptor (EGFR), human epidermal growth factor receptor 2 (HER2), and carcinoembryonic antigen (CEA) have significant diagnostic and prognostic values as tumor biomarkers." (PMID 36839030, 2023). "HCD3514 dose-dependently inhibited the activation of EGFR in both engineered BaF3 cells and tumor cells harboring EGFRC797S triple mutant and thus effectively suppressed the proliferation of the cells." (PMID 36605493, 2023). "Here, we investigated the efficacy of vertical inhibition of the RAS‐pathway by targeting epidermal growth factor receptor (EGFR) and mitogen‐activated protein kinase kinase (MEK) in patient‐derived xenograft (PDX) tumours with primary KRAS mutation." (PMID 37604687, 2023). "The aim of this study focused to investigate the prevalence of acquired genomic alterations and the role of RAS ctDNA status for detecting early tumour response and predicting benefit to anti-EGFR therapy." (PMID 37488448, 2023).